GDNF (glial cell derived neurotrophic factor)
Diseases named in the same sentence as GDNF in open-access papers (continued):
Sharing a sentence is not in itself a finding about the gene and the disease.
neurodegenerative disease (continued). "In such a situation, GDNF evaluation could be used as a marker of future neuroprotective therapies’ effectiveness in various neurodegenerative diseases, yet further studies are needed to confirm its usefulness in such a role." (PMID 41465547, 2025). "In the case of potential therapy for neurodegenerative diseases, GDNF has a relatively high specificity for dopaminergic neurons and, thus, has significant potential for the treatment of PD, which is mainly characterized by progressive depletion of dopaminergic cell populations in the midbrain." (PMID 36835277, 2023). "GDNF is shown to be one of the main factors produced by glial cells for neuronal viability in stress conditions and plays important neuroprotective role in neurodegenerative disease." (PMID 36077134, 2022). "We hypothesize that the variation in the anti-inflammatory effects of GDNF could be the consequence of the different pathological properties induced by the misfolding of each set of proteins characteristic of each neurodegenerative disease." (PMID 34769132, 2021). "Nevertheless, the new approach using GDNF to prevent neuroinflammation at early steps in neurodegeneration could be the light at the end of the road to treat some types of neurodegenerative diseases." (PMID 34769132, 2021). "Although the Rheb–mTOR signaling pathway may act as a double-edged sword in neurodegeneration, it is a central regulator of NTFs such as BDNF, CNTF, and GDNF and thus is a potential therapeutic target for neurodegenerative diseases." (PMID 32188096, 2020). "Aβ levels are one of the most extensively evaluated markers of sporadic AD, since GDNF was identified as potential AD biomarker, could we suggest it as a general biomarker of neurodegenerative diseases?" (PMID 29899726, 2018). "Neurons that secrete GDNF might have higher survival rates after grafting in animal models of neurodegenerative diseases." (PMID 27672361, 2016). "Discovery of growth factors and their pro-survival effect led to a closer investigation of specific nervous system cytokines - Nerve Growth Factor (NGF), Brain-Derived Nerve Factor (BDNF), Glial-Derived Nerve Factor (GDNF) - involvement in the outcome of neurodegenerative diseases." (PMID 21699711, 2011). "Hence, GDNF is shown to be neuroprotective and supporting dopaminergic neurons in PD models, and thus, could potentially be utilized as a therapy against neurodegenerative diseases, especially PD." (PMID 31744191, 2019). "Although increased GDNF levels in the central nervous system (CNS) may be beneficial to the treatment of neurodegenerative diseases, such as PD and drug addiction, the therapeutic application of GDNF is limited because efficient methods of delivering it to the CNS are currently not available." (PMID 23300823, 2012). "In contrast, in neurodegenerative disease, elevated BDNF mRNA was observed in astrocytes surrounding amyloid plaques, while GDNF mRNA was elevated in astrocytes of lesioned striatum in the 6-hydroxydopamine (6-OHDA) model of PD." (PMID 36768317, 2023). "Moreover, edaravone shows consistent in-vivo efficacy to activate the GDNF/RET signaling in mouse spinal cord samples, justifying more studies in mouse models of ALS and other neurodegenerative diseases that may benefit from neuroprotection through GDNF/RET activation." (PMID 35012575, 2022). "It has been reported that glial cell-derived neurotrophic factor (GDNF) exhibits a prominent neurorestoration and neuroprotection in multiple neurodegenerative diseases, including PD." (PMID 33902532, 2021). "Glial cell line-derived neurotrophic factor (GDNF) has a pronounced neuroprotective effect in various nervous system pathologies, including ischaemic brain damage and neurodegenerative diseases." (PMID 31827666, 2019). "Since submaximal doses of two proteins, CDNF and GDNF, lead to full effect, less NTF is needed, less side effects will likely occur and possible drug therapy for degenerative diseases will be cheaper." (PMID 28303260, 2017).
neurodegenerative disease (continued). "For example, genetic alterations can enhance NSC functionality by promoting the release of neurotrophic factors such as brain-derived neurotrophic factor (BDNF) and glial cell line-derived neurotrophic factor (GDNF), which are vital for neuronal sustenance in neurodegenerative diseases." (PMID 40612293, 2025). "GDNF and BDNF could be useful for prospective studies involving the development of neurodegenerative diseases in IBD patients." (PMID 38891863, 2024). "In neurodegenerative diseases, synthetic mRNA can be used to produce neuroprotective factors like brain-derived neurotrophic factor (BDNF) or glial cell line-derived neurotrophic factor (GDNF), supporting neuronal health and survival." (PMID 39684324, 2024). "When the levels of CaMkII and AMPK are reduced at the onset of neurodegenerative disease, the consequent reduced ability to express PGC-1α, FNDC5, BDNF, NGF, and GDNF could lead to cognitive dysfunction and deteriorating physical fitness." (PMID 35805580, 2022). "The glial cell line-derived neurotrophic factor (GDNF), a survival-promoting molecule for midbrain dopaminergic neurons, was originally identified as a potential therapeutic agent for the treatment of neurodegenerative diseases." (PMID 33413640, 2021). "In addition, they have been found to produce NTFs such as GDNF and CNTF in animal models of neurodegenerative diseases." (PMID 32188096, 2020). "Neurotrophic factors (NTFs), such as nerve growth factor (NGF), brain-derived neurotrophic factor (BDNF) and glial cell-line derived neurotrophic factor (GDNF), play pivotal roles in neuronal development and survival and exhibit therapeutic potential in animal models of neurodegenerative diseases." (PMID 23923031, 2013). "The role of GDNF in neurodegenerative diseases is not recognized." (PMID 38307947, 2024). "In addition to the increased pro-inflammatory mediators in the brain in neurodegenerative diseases, neurotrophic factors, such as brain-derived neurotrophic factor (BDNF), glial cell-derived neurotrophic factor (GDNF) and insulin-like growth factor (IGF)-1, are impaired in these diseases." (PMID 26729090, 2015).
neurological disorders (28 papers, 2012 to 2025). "GDNF serum level has enormously implicated in many other neurological disorders." (PMID 35095724, 2021). "Since its identification, GDNF, along with other GFLs, has sparked significant interest in the scientific community for its potential as a therapeutic agent in treating various neurological disorders." (PMID 40642294, 2025). "Promoting BDNF and GDNF release is a promising therapeutic strategy for the treatment of neurological disorders." (PMID 40904189, 2025). "LM11A-31, which is planning for a Phase III clinical trial for AD, along with GDNF gene therapy for neurological diseases, are among the most advanced therapeutic strategies." (PMID 41562905, 2025). "It is widely known that glial cell-derived neurotrophic factor (GDNF) exerts a robust neuroprotective effect in various neurological diseases." (PMID 38008847, 2023). "Among other factors, GDNF is supposed to be highly involved in neuronal function and brain diseases, and its use in the diagnostics, prognosis, and treatment of neurological diseases is extensively studied and debated." (PMID 38069144, 2023). "GDNF therapy has been similarly used in other neurological diseases where negative regulation of GDNF precedes nerve damage." (PMID 34769132, 2021). "Enhancing our understanding of GDNF and its signaling pathways will allow for the discovery of possible therapeutic approaches for applications of a broad range of neurological disorders such as ALS." (PMID 32897420, 2020). "This work illustrates the power of the canine model in genetics and shows the potential implication of GDNF in such neurological diseases, revealing the importance to explore this gene and its regulatory elements as serious candidates in human HSAN patients." (PMID 28033318, 2016). "Taken together, promotion of BDNF and GDNF release are recognized to hold a promising therapeutic strategy for the treatment of neurological disorders." (PMID 23304227, 2012). "Moreover, there are studies embarked on GDNF serum level vs. neurological diseases." (PMID 35095724, 2021). "Modulating neurotrophins—the brain-derived neurotrophic factor (BDNF), glial cell line-derived neurotrophic factor (GDNF), and ciliary neurotrophic factor (CNTF)—support neurogenesis, neuroprotection, and synaptic plasticity in neurologic disorders." (PMID 40943142, 2025). "The neurotrophic role of mesencephalic astrocyte derived neurotrophic factor (MANF) and cerebral dopamine neurotrophic factor (CDNF) has been demonstrated in several models of neurological diseases and crosstalk with BDNF and GDNF." (PMID 36338029, 2022). "Brain-derived neurotrophic factor (BDNF)-overexpressing hNSPCs, glial cell line-derived neurotrophic factor (GDNF)-overexpressing hNSPCs, and insulin-like growth factor 1 (IGF-1)-overexpressing hNSPCs have all been shown significant therapeutic effects on neurological disorders." (PMID 34827135, 2021). "Moreover, the relevance of oxidative stress and the potential benefit of such factors as BDNF, GDNF and IGF-1 in multiple other neurological diseases (e.g. ALS and Huntingdon's chorea) indicate obvious potential applications of GDAsBMP in other settings." (PMID 24477866, 2014). "In neurological disorders, bioactive factors such as nerve growth factor (NGF) promote stem cell differentiation into neural-like cells, while brain-derived neurotrophic factor (BDNF) and glial cell-derived neurotrophic factor (GDNF) enhance neurite outgrowth and Schwann cell function." (PMID 40710251, 2025). "Similarly, NSCs stable-expressing neurotrophies, such as glial cell-derived neurotrophic factor (GDNF), brain-derived neurotrophic factor (BDNF), and NGF, exhibited remarkably improved proliferation, survival, and functional recovery in different neurologic disease animal models." (PMID 34135002, 2021).
infection (14 papers, 2012 to 2025). The state of being infected such as from the introduction of a foreign agent such as serum, vaccine, antigenic substance or organism. "Infection with this virus also results in a decrease in brain-derived neurotrophic factor (BDNF) and glial cell-derived neurotrophic factor (GDNF), which encode key factors essential for maintaining neural plasticity." (PMID 39840010, 2024). "GDNF transcription was significantly decreased and increased by infection with sgRNA-CRE-E (P < 0.05) and sgRNA-CRE-S (P < 0.01), respectively." (PMID 32183903, 2020). "Finally, in another context, the infection with the bacterium Streptococcus pneumoniae, causing diseases such as pneumonia, sinusitis and meningitis, alters the expression level of GDNF in the olfactory bulb, which could indirectly influence microglial activation." (PMID 32252363, 2020). "Infection and catheter misplacement were reported as postoperative complications in the double-blind placebo-controlled study of stereotactic injection of GDNF." (PMID 29615705, 2018). "The GDNF decrease from 33 days post-infection (38 days post-seeding) was presumably due to a reduced number of neurons in aging cultures which were previously shown to undergo apoptosis (data not shown)." (PMID 23301037, 2013). "The GDNF concentration increased over time until 26 days post-infection (corresponding to 31 days post-seeding), then decreased." (PMID 23301037, 2013). "Furthermore, it has been demonstrated that rAAV5-GDNF gene infections in the red nucleus resulted in GDNF-positive fibers projecting into spinal gray matter; however, cortical infections drew less evident staining in the spinal cord." (PMID 23202963, 2012). "This may be due to the infection-increased expression of GDNF." (PMID 31964731, 2020). "Following injury or infection, EGC release GDNF, which contributes to the protection of the intestinal epithelial cells, by upregulating the expression of the tight junction proteins." (PMID 32252363, 2020). "To assess neurotrophic factor (NTF) effects on acute replication of HSV1 and HSV2 in adult sensory neurons, we deprived cultured TG neurons of either NGF, GDNF, or NTN during acute infection for 24 h." (PMID 28178213, 2017). "First, we demonstrated that brain-derived neurotrophic factor (BDNF), glial-derived neurotrophic factor (GDNF), neurotrophin-3 (NT3), and their combinations (GBN) could significantly inhibit WSN infection at the NESTIN+ NSCs level, especially BDNF and GBN in NP+ cells." (PMID 35910807, 2022). "Importantly, GDNF–mCherry expression could not be detected in the spinal cord explant at 5 days after infection of myocytes (data not shown), indicating that virions could not diffuse to the motoneuron cell body compartment and did not infect motoneurons." (PMID 25632161, 2015).
psychiatric disorder (12 papers, 2013 to 2025). A disorder characterized by behavioral and/or psychological abnormalities, often accompanied by physical symptoms. "For example, no reliable associations were found between the frequency of trinucleotide repeats (AGG)n (and a number of GDNF missense mutations) and the incidence of psychiatric disorders in a Japanese population." (PMID 38646100, 2024). "Recently, research has found a relationship between BDNF and GDNF and the occurrence of mental illness." (PMID 37509026, 2023). "In contrast, plasma concentrations of GDNF and BDNF/proBDNF were reduced in individuals with psychiatric disorders and those with suicides caused by life events." (PMID 37509026, 2023). "GDNF and BDNF are markers that play a fundamental role in synaptic plasticity, which is associated with the pathogenesis and treatment of psychiatric disorders." (PMID 34763683, 2021). "In conclusion, our data suggest the involvement of state- (i.e., HGF, S100B, and VEGF receptor 2) and trait (i.e., APP, GDNF, and NCAM-1) markers associated with neuroplasticity in the pathology of psychiatric disorders." (PMID 32439851, 2020). "Our results suggest that CSF APP, GDNF, and NCAM-1 levels are associated with psychiatric disorders, and that CSF HGF, S100B, and VEGF receptor 2 levels are related to psychiatric symptoms." (PMID 32439851, 2020). "However, the role of GDNF as a biomarker in psychiatric disorders—particularly SCZ—remains a topic of ongoing debate." (PMID 39881227, 2025). "In addition, we analyzed changes in TPH2, BDNF, and GDNF in mental illness suicide (PI) and life event suicide (LE)." (PMID 37509026, 2023). "At the same time, only a small number of studies have been devoted to investigating the relationship between the occurrence of GDNF genomic variants and the predisposition to psychiatric disorders, with no reliable data obtained to definitively confirm such correlations." (PMID 38646100, 2024). "Finally, it cannot be determined whether the alteration of expression, processing or clearance of significant proteins (i.e., APP, GDNF, HGF, NCAM-1, S100B, and VEGF receptor 2) results in the association with psychiatric disorders." (PMID 32439851, 2020). "Studies in English and Chinese populations also revealed no functional significance of GDNF polymorphisms: (AGG)n, rs2910709-C/G/T (3′ downstream), rs2973050-C/G/T (intr), rs884344-C (intr), rs2910702-A/T (intr), rs2216710-T (intr), rs3812047-G/T (intr), etc. in the development of mental disorders." (PMID 38646100, 2024).
brain diseases (11 papers, 2014 to 2023). "Up-regulation of GDNF by astrocytes and microglia may be a protective mechanism to restrain neuronal loss observed in different types of brain diseases." (PMID 34078872, 2021). "Our study provides a new approach to locally open the BBB and target delivery of neurotrophic factors, such as GDNF, to treat brain diseases like addiction." (PMID 36046678, 2022). "This technique can avoid brain tissue damage caused by intracranial microinjection, and further increases the advantages of neurotrophic factors, such as GDNF, in the treatment of brain diseases." (PMID 36046678, 2022). "Moreover, the loss of neurotrophic factors such as glial cell line-derived neurotrophic factor (GDNF) and brain-derived neurotrophic factor (BDNF) with CNTF may be involved in the pathogenesis of brain diseases." (PMID 25799580, 2015).
neuromuscular disease (6 papers, 2018 to 2024). "GDNF is largely studied in various neurological and neuromuscular diseases, with a great interest in the peripheral nervous system (PNS)." (PMID 29899726, 2018). "Aging and neuromuscular diseases such as ALS are associated with adverse changes in the morphology and function of the neuromuscular junction, whereas exercise has opposing effects, potentially mediated through increased GDNF protein expression." (PMID 37920126, 2024). "Importantly, GDNF is particularly involved in the pathophysiology of various neurological and neuromuscular diseases, with a great interest in the peripheral nervous system (PNS)." (PMID 29899726, 2018).
neurodevelopmental disorder (5 papers, 2023 to 2025). A behavioral and cognitive disorder with onset during the developmental period that involves impaired or aberrant development of intellectual, motor, or social functions. "Our result of under-expression also supports previous research such as the study conducted where the authors show that low levels of GDNF are associated with synapse dysregulation and neuronal shrinkage, both of which are characteristic neuropathological features in neurodevelopmental disorders." (PMID 39502974, 2024).
inflammation (4 papers, 2011 to 2025). Aberrant reaction of the microcirculation characterized by movement of fluid and leukocytes from the blood into extravascular tissues. "Interestingly, increased GDNF levels and 5-HT+ cell frequency have been previously connected to intestinal inflammation." (PMID 39634560, 2024).
renal disease (3 papers, 2013 to 2024). "Except GDNF, all LN-associated markers showed usefulness in prediction of active renal disease." (PMID 29026368, 2017). "We also found, using the Olink proteomic platform, that TNF-α and TMAO enhanced the secretion of additional inflammatory-and growth mediators associated with kidney disease; VEGFA, GDNF, CDCP1, OPG, uPA, AXIN1, MMP-1, MMP-10, PD-L1, HGF, Flt3L, 4E-BP1, CD40, CASP-8, ADA, TNFRSF9, TWEAK44–61." (PMID 38643262, 2024). "Moreover, we observed good discrimination between active and inactive renal disease in LN patient subgroup for all markers, except for GDNF." (PMID 29026368, 2017). "When LN patients with active renal disease was compared to inactive LN subgroup, elevation of sIL15RA, CSF1, bNGF, sIL18R1, sCD40, sCX3CL1, and caspase 8 (P < 0.05), but not GDNF, in active LN patients was observed." (PMID 29026368, 2017). "The analysis in biopsy-proven LN patients with active renal disease revealed elevated protein levels of CSF1, sIL15RA, sCD40, sCX3CL1, caspase 8, sIL18R1, bNGF, and GDNF compared to those without LN." (PMID 29026368, 2017). "Our serum protein analysis in LN patients with active renal disease revealed upregulated levels of CSF1, sIL15RA, sCD40, sCX3CL1, caspase 8, sIL18R1, bNGF, and GDNF compared to those without LN." (PMID 29026368, 2017).
adenocarcinoma (2 papers, 2018 to 2022). A common cancer characterized by the presence of malignant glandular cells. "GDNF as well as NTN were expressed at high levels in adenocarcinoma cells." (PMID 35927360, 2022).
colonic (1 paper, 2020). "To investigate the potential role of GDNF in acute stress‐related disorders in the intestine, we adopted a WRS model which was an adequate model to mimic part of the main symptoms of IBS, such as pain and colonic dysmotility." (PMID 32808420, 2020).
colorectal (1 paper, 2018). "GDNF has been reported to be hypermethylated in colorectal carcinogenesis; however, reduced inactivation of GDNF may also contribute to FAP tumorigenesis." (PMID 30220972, 2018).